NRAS (NRAS proto-oncogene, GTPase)
Diseases named in the same sentence as NRAS in open-access papers (continued):
Sharing a sentence is not in itself a finding about the gene and the disease.
vascular malformation (2 papers, 2021 to 2022). A non-neoplastic disorder that is the result of defects of vascular morphogenesis. "And recurrently mutated genes were identified in several vascular malformations as well including TEK/TIE2 mainly in venous malformations, GNA11/14 mainly in vascular tumors, KRAS/NRAS/RASA1/HRAS mainly in AVMs, GNAQ, IDH1/2, AKT1, PTEN and PIK3CA." (PMID 34736485, 2021). "Except for the previous mentioned article, no other studies on infantile hemangiomas or other vascular malformations reporting NRAS gene involvement have been published." (PMID 35740845, 2022).
Wilms tumor (2 papers, 2019 to 2025). An embryonal neoplasm characterized by the presence of epithelial, mesenchymal, and blastema components. "In conclusion, this was the first multi-center evaluation of the association of KRAS and NRAS gene SNPs with Wilms tumor susceptibility." (PMID 30860980, 2019). "Herein, we evaluated the impact of KRAS and NRAS gene SNPs on the risk of Wilms tumor in 355 Wilms tumor patients and 1070 healthy control subjects." (PMID 30860980, 2019). "Stratification analysis for the association between NRAS rs2273267 A>T polymorphism and Wilms tumor risk." (PMID 30860980, 2019). "To clarify the association of RAS with Wilms tumor risk, we selected single-nucleotide polymorphisms (SNPs) in the two most common diseased-related RAS genes, KRAS and NRAS, for analysis in a four-center hospital-based case-control study." (PMID 30860980, 2019).
acute erythroid leukemia (1 paper, 2016). An acute myeloid leukemia characterized by a predominant immature erythroid population.
apocrine carcinomas (1 paper, 2025).
bipolar disorder (1 paper, 2018). A disorder of the brain that causes unusual shifts in mood, energy, activity levels and the ability to carry out day-to-day tasks. "Further schizophrenia and bipolar disorder patients have shown higher expression of two different targeted genes: NRAS and CDC25B, respectively, in the frontal cortex than controls." (PMID 29745862, 2018). "We identified four rSNP-targeted genes that showed differential expression between patient and control groups depending on brain region: NRAS—in schizophrenia cohort, CDC25B, DDX21 and NUCKS1—in bipolar disorder cohort." (PMID 29745862, 2018). "As a result of analysis by DeSeq 2.0, NRAS and CDC25B targeted genes happened to be DE in the frontal cortex of schizophrenia-vs-controls and bipolar-disorder–vs-controls groups, respectively when considering a significance threshold of adjusted P value ≤ 0.1 after correcting for multiple testing." (PMID 29745862, 2018).
brain cancer (1 paper, 2021). A primary or metastatic malignant neoplasm affecting the brain. "Accordingly, based on our sequencing results, NRAS v9 is predominantly expressed in breast and brain cancer." (PMID 34948093, 2021).
breast sarcoma (1 paper, 2013). A malignant mesenchymal neoplasm that arises from the breast. "Our genomic analysis reports for the first time a mutation in the NRAS gene in breast sarcomas." (PMID 23895135, 2013).
carcinoid tumor (1 paper, 2015). A slow growing neuroendocrine tumor, composed of uniform, round, or polygonal cells having monotonous, centrally located nuclei and small nucleoli, infrequent mitoses, and no necrosis. "None of the BRAF, KRAS, NRAS, or PIK3CA mutations were detected in the carcinoid tumors; moreover, none of the 56 cases exhibited MSI-high status." (PMID 26090613, 2015).
childhood cancers (1 paper, 2020). "Abnormalities in six genes (NRAS, ABL1, JAK2, KIT, ALK and BRAF) were common in childhood cancers as well as adult cancers, for which at least one approved drug could be a potentially actionable drug." (PMID 33051474, 2020).
chronic obstructive pulmonary disease (1 paper, 2017). A chronic and progressive lung disorder characterized by the loss of elasticity of the bronchial tree and the air sacs, destruction of the air sacs wall, thickening of the bronchial wall, and mucous accumulation in the bronchial tree. "Navarixin has been successful in alleviating pulmonary inflammation in patients with chronic obstructive pulmonary disease and would be worth testing in patients at risk of lung metastasis from NRAS‐mutant tumors." (PMID 28341702, 2017).
CNS melanocytic tumors (1 paper, 2014). "For patients with NRAS-mutated CNS melanocytic tumors, treatment with MEK162 might be of benefit as well." (PMID 25593912, 2014).
Cognitive impairment (1 paper, 2023). Abnormal cognition is characterized by deficits in thinking, reasoning, or remembering. "Seven differentially expressed autoantibodies were recognised as cognitive impairment-related, including HSPD1, CDK19, TKT, BRSK2, NRAS, LMNA, and CAMK2A." (PMID 38107644, 2023).
diabetes (1 paper, 2025). "The AKT and NRAS genes are associated with somatic mutations in individuals with and without diabetes." (PMID 41291320, 2025).
diabetic nephropathy (1 paper, 2022). "It was also observed that hispidulin modulated multiple Pim1-interacted proteins such as NRAS and RAB18 to regulate the development of diabetic nephropathy." (PMID 34028657, 2022).
familial melanoma (1 paper, 2011). Familial melanoma (FM) is a rare inherited form of melanoma characterized by development of histologically confirmed melanoma in two first degrees relatives or more relatives in an affected family. "A similar finding was previously reported in familial melanoma, with CDKN2A as well as BRAF and NRAS mutations." (PMID 22039425, 2011).
germinoma (1 paper, 2016). A malignant germ cell tumor arising in the central nervous system. "We examined a total of 51 germinomas and 1 mixed GCT (germinoma and teratoma component) for mutations in KIT exons 11, 13, 17 and 18 as well as mutation hotspots in HRAS, KRAS, NRAS and RRAS-2." (PMID 27391150, 2016).
gynecological cancer (1 paper, 2019). "Similar results were also reported for AZD5363, although exclusive PIK3CA mutations did not correlate with increased response in another study in breast or gynecological cancer patients where concurrent mutations in KRAS, NRAS, HRAS, or BRAF were excluded." (PMID 31835495, 2019).
Hashimoto thyroiditis (1 paper, 2023). An autoimmune disorder caused by the production of autoantibodies against thyroid tissue. "Multivariate logistic regression analysis revealed that sex, Hashimoto’s thyroiditis (HT), tumor size, extrathyroidal extension, TERT promoter mutations and NRAS mutation were independent factors of CLNM." (PMID 36817603, 2023).
hemimegalencephaly (1 paper, 2014). "In summary, development of a primary intracerebral mesenchymal neoplasm in a child with NCMS and hemimegalencephaly can likely be explained by specific NRAS mutant mosaicism possibly in combination with a MET germline variation, which together constitute a unique combination." (PMID 25330907, 2014).
hemochromatosis (1 paper, 2018). A disorder of iron metabolism characterized by a triad of HEMOSIDEROSIS; LIVER CIRRHOSIS; and DIABETES MELLITUS. "Examples are mitogen-activated protein kinase (MAPK)/RAS family members (HRAS and NRAS), hemochromatosis (HFE), BRD7, ATM, vimentin (VIM), which are upregulated in poorly differentiated cell lines and in human HCC datasets." (PMID 30176945, 2018).
Hepatitis (1 paper, 2022). Inflammation of the liver. "We next tested other possible clinical, oncological (BRAF/NRAS status, stage, LDH levels, presence of metastasis), virological or hepatological characteristics of our patient cohorts that might contribute to ICB-hepatitis during dural checkpoint therapy in the pooled cohort." (PMID 36503532, 2022).
hypertensive nephropathy (1 paper, 2024). Kidney damage that results from chronically elevated blood pressure; complications include glomerular damage resulting in proteinuria and hematuria. "The expression of KRAS, MAPK1, NRAS, and PTEN was significantly upregulated in the tubulointerstitial region of patients with hypertensive nephropathy compared with healthy living donors." (PMID 39199205, 2024). "Similarly, the expression of MAPK1, NRAS, and PTEN was also significantly upregulated in the glomeruli of patients with hypertensive nephropathy." (PMID 39199205, 2024). "Collectively, in the hypertensive nephropathy samples and AngII-induced podocyte models, the renal injury markers were increased, autophagic flux was decreased, and differential miRNAs (miR-98-5p and miR-669b-5p), hub target genes (KRAS and NRAS), and transcription factor (RUNX2) were dysregulated." (PMID 39199205, 2024).
in situ carcinoma (1 paper, 2022). A malignant epithelial neoplasm which is confined to the epithelial layer without evidence of further tissue invasion. "The second mentioned NRAS mutation was observed in in situ carcinoma in our set of patients." (PMID 35173208, 2022).
ischemic stroke (1 paper, 2025). A stroke disorder caused by obstruction of blood flow to the brain, due to thrombotic (local blood clot formation) or embolic (due to a blood clot or other material traveling from another site) event. "Among them, FTH1, SLC40A1, NRAS, CD82, and PTPN18 emerged as potential key targets underlying the antiferroptotic effects of acupuncture on ischemic stroke." (PMID 40552324, 2025). "Bioinformatics analysis and RT-qPCR suggested that FTH1, SLC40A1, NRAS, CD82, and PTPN18 might serve as potential key targets underlying the antiferroptotic effects of acupuncture on ischemic stroke." (PMID 40552324, 2025). "Enhancing the expression of the NRAS gene could be an important target for acupuncture in the treatment of ischemic stroke, as it may inhibit ferroptosis by decreasing iron accumulation and reducing erastin." (PMID 40552324, 2025). "The results demonstrated that the expression levels of FTH1, SLC40A1, NRAS, CD82, CD44, and PTPN18 were upregulated in mice with ischemic stroke following acupuncture treatment." (PMID 40552324, 2025). "Moreover, FTH1, SLC40A1, NRAS, CD82, and PTPN18 levels significantly increased after acupuncture in ischemic stroke mice." (PMID 40552324, 2025).
Kaposi's sarcoma (1 paper, 2022). A malignant neoplasm characterized by a vascular proliferation which usually contains blunt endothelial cells. "All LM cases with Kaposi sarcoma-like (kaposiform) histology had NRAS mutations." (PMID 35787784, 2022).
kaposiform hemangioendothelioma (1 paper, 2022). Kaposiform hemangioendothelioma is a very rare, aggressive, vascular tumor manifesting in the neonatal period or in infancy as cutaneous vascular tumors to large infiltrative lesions. "A somatic activating NRAS mutation was detected in kaposiform lymphangiomatosis but not in kaposiform hemangioendothelioma." (PMID 35740845, 2022).
lymphopenia (1 paper, 2023). Reduction in the number of lymphocytes.
mast cell leukemia (1 paper, 2025). Mast cell leukemia is a malignant form of systemic mastocytosis (SM) characterized, most of the time, by the presence of circulating mast cells.
meningeal melanoma (1 paper, 2024). "Furthermore, some additional molecular alterations, such as SF3B1, EIF1AX, and BAP1 mutations, confer a significant aggressive course in meningeal melanoma, while both primary diffuse leptomeningeal melanocytosis or melanomatosis are often NRAS mutated and rarely BRAF mutated." (PMID 39061148, 2024).
mesonephric adenocarcinoma (1 paper, 2019). An adenocarcinoma of the cervix or the vagina arising from mesonephric remnants. "KRAS/NRAS mutations are the most common molecular alterations detected in mesonephric adenocarcinomas." (PMID 31266530, 2019).
metastatic colon tumors (1 paper, 2024). "Notably, the limited data available on patients with concurrent NRAS mutations reveal an even more unfavorable prognosis, particularly in patients with metastatic colon tumors, and may be associated with a diminished response to conventional chemotherapy treatments." (PMID 38786299, 2024).
monocytic leukemia (1 paper, 2023). "PTPN11mut was more common in myelomonocytic and monocytic leukemia, and was more likely to co‐mutate with KRAS, KMT2C, NRAS, U2AF1, NOTCH1, IKZF1, and USH2A mutations than PTPN11wt." (PMID 37937729, 2023).
multiple sclerosis (1 paper, 2025). A progressive autoimmune disorder affecting the central nervous system resulting in demyelination. "Currently, we have used single genes to predict the prognosis of patients and found that both NRAS and KLF2 are good diagnostic genes for multiple sclerosis, and they could independently predict the onset of multiple sclerosis." (PMID 38886317, 2025).
myocardial infarction (1 paper, 2024). Gross necrosis of the myocardium, as a result of interruption of the blood supply to the area, as in coronary thrombosis. "During myocardial infarction, aberrant activation or mutations of NRAS might impede normal functioning of these signaling pathways, thus affecting myocardial cell survival and function." (PMID 38818463, 2024).
myocardial ischemia (1 paper, 2024). A disorder of cardiac function caused by insufficient blood flow to the muscle tissue of the heart. "Gene-metabolite interaction network analysis revealed the significant roles of key regulatory molecules such as HIF1A, adenosine, TBK1, ATP, NRAS, and EIF2AK3, in the pathogenesis of myocardial ischemia." (PMID 38818463, 2024).
myocarditis (1 paper, 2025). Myocarditis is a condition that is characterized by inflammation of the heart muscle (myocardium). "The identification of the miR-425a-5p/NRAS axis provides novel molecular perspectives on myocarditis pathogenesis and potential therapeutic interventions." (PMID 40433545, 2025). "We demonstrated that miR-425-5p alleviates myocarditis through the regulation of NRAS and subsequent modulation of TREG cell differentiation." (PMID 40433545, 2025).
neuroendocrine neoplasm (1 paper, 2022). Endocrine tumors, also referred to as neuroendocrine tumors (NETs), are defined by a common phenotype which is characterized by the expression of general markers (neuron specific enolase, chromogranin, synaptophysin) and hormone secretion products. "However, mutations in various genes related to TKs were detected in the tumor samples (JAK3, NRAS, NTRK2, NF1, SETD2) suggesting frequent alteration of TK pathways for neuroendocrine neoplasms." (PMID 36743926, 2022).
osteoarthritis (1 paper, 2018). A noninflammatory degenerative joint disease occurring chiefly in older persons, characterized by degeneration of the articular cartilage, hypertrophy of bone at the margins and changes in the synovial membrane. "Our research suggests that the FOS gene plays a key role in the synovitis of osteoarthritis, and the NRAS gene indirectly acts on FOS, which provides the theoretical basis and ideas for further experimental study." (PMID 29968759, 2018).
ovarian clear cell cancer (1 paper, 2024). An invasive malignant neoplasm that arises from the ovary and is characterized by a predominance of clear and hobnail malignant epithelial cells. "In ovarian clear cell carcinoma, no NRAS mutations were found in transcriptome data." (PMID 39349928, 2024).
peripartum cardiomyopathy (1 paper, 2018). Peripartum cardiomyopathy (PPCM) is an idiopathic, potentially fatal form of dilated cardiomyopathy that develops during the final month of pregnancy or within five months after delivery. "In addition to tumorigenesis, reduction of NRAS using siRNA or miR-146a reduced the proliferation rate and increased apoptosis in human umbilical vein endothelial cells (HUVECs), resulting in further involvement in peripartum cardiomyopathy." (PMID 30225000, 2018).
Peritoneal Cancer (1 paper, 2023). A peritoneum cancer that is located in the inside of the abdomen. "Nodal involvement, extramural vascular invasion, Peritoneal Cancer Index (PCI) score, CC score, SACT post-HIPEC and NRAS mutation were significant negative predictors of OS in univariate analysis (p < 0.05)." (PMID 36400886, 2023).
phyllodes tumor (1 paper, 2013). A benign, borderline, or malignant fibroepithelial neoplasm arising from the breast and rarely the prostate gland. "We describe for the first time an NRAS mutation with concomitant activation of PI3K/Akt/mTOR in phyllodes tumor." (PMID 23895135, 2013).
pituitary adenomas (1 paper, 2020). "In the total cohort, the most common oncotype in pituitary adenoma-related DTC was classical-variant PTC (9 out of 14 cases) with a high frequency (42.9%, 6/14) of BRAF (p.V600E) mutations, whereas none of these cases harbored NRAS mutations." (PMID 32333269, 2020).
pneumocystis pneumonia (1 paper, 2021). "The single patient with an NRAS mutation who did not die of an infection nevertheless had an episode of severe and prolonged neutropenic sepsis after her first course of chlorambucil, followed by pneumocystis pneumonia 3 years later after completing second-line treatment with fludarabine." (PMID 33580200, 2021).
polycythemia vera (1 paper, 2020). "In another study in which targeted cancer exome sequencing was performed in BCR-ABL-negative MPNs, NRAS mutations were found in only 4.7% of 168 patients with primary myelofibrosis (MF) and in none of the patients with polycythemia vera (PV)." (PMID 32344757, 2020).
primary immunodeficiency disease (1 paper, 2025). "For instance, Ras-associated autoimmune lymphoproliferative disorder (RALD) is a sporadic primary immunodeficiency disease caused by somatic mutations in the KRAS and NRAS genes, which result in ALPS-like manifestations." (PMID 40364944, 2025).
reactive disorder (1 paper, 2025). "Recent studies have shown that approximately one-third of patients with RDD harbor mutations in genes involved in the MAPK/ERK pathway, such as NRAS, KRAS, MAP2K1, and, rarely, BRAF, indicating a neoplastic process rather than a reactive disorder." (PMID 40385897, 2025).
rectal mucinous adenocarcinoma (1 paper, 2025). "The second patient was female with rectal mucinous adenocarcinoma and synchronous bone metastases and presented with KRAS c.35G>T (p.Gly12Val) and NRAS c.38G>T (p.Gly13Val) mutations." (PMID 40075837, 2025).
renal failure (1 paper, 2023). "Combining the most common mutations in cell signaling genes such as NRAS, CBL, and JAK2, the prevalence of these aberrations was 55% in CMML patients with renal failure as compared to 38% among patients with normal kidney function (p = 0.056)." (PMID 36282402, 2023).
Rosai-Dorfman disease (1 paper, 2025). "Recent research has revealed that the development of Rosai-Dorfman disease (RDD) may be closely linked to specific genetic mutations, such as BRAF, KRAS, and NRAS involving in the abnormal activation of the MAPK/ERK signaling pathway." (PMID 40018414, 2025).